IL6 (interleukin 6)
Diseases named in the same sentence as IL6 in open-access papers (continued):
Sharing a sentence is not in itself a finding about the gene and the disease.
depression (continued). "In addition, the clinical evidence suggests increased pro-inflammatory markers in patients with depression (increased TNF-α, CRP, and IL-6)." (PMID 31258489, 2019). "A considerable body of evidence suggests that individuals with diagnosed depression exhibit significantly higher levels of IL-1, IL-6, TNF-α, and C-reactive protein (CRP) compared to non-depressed counterparts." (PMID 31068783, 2019). "Moreover, IL-6 reportedly plays an important role in the main symptoms of CFS, such as hyperalgesia, fatigue, sleep impairment, and depression." (PMID 31253154, 2019). "Depressive disorder was found to link with an increase in expression of various central and peripheral proinflammatory cytokines, including tumor necrosis factor α (TNF-α) and interleukin-1, interleukin-6 (IL-1, IL-6), and interferon- α and γ." (PMID 31881712, 2019). "Compared with controls, IL-1β (pooled standardized mean difference [SMD]: 0.642; 95% confidence interval [CI]: 0.078–1.206; significant heterogeneity: I2 = 86.28%) and IL-6 (pooled SMD: 0.377; 95% CI: 0.156–0.598; significant heterogeneity: I2 = 88.75%) were significantly elevated in depression." (PMID 30104698, 2018). "There were no systematic hs-CRP or IL-6 correlations with clinical PANSS subscale scores or Calgary depression self-ratings (data not shown)." (PMID 30322824, 2018). "In this meta-analysis, we found that elderly with depression had significantly higher peripheral levels of IL-1β (p = 0.026), IL-6 (p < 0.001) but not TNF-α (p = 0.351) and CRP (p = 0.05)." (PMID 30104698, 2018). "The genetic variant is strongly associated with serum IL-6 and CRP levels, but not with any common confounders of the inflammation–depression relationship such as sex, social class, ethnicity and body mass index." (PMID 30244217, 2018). "In addition, resveratrol supplementation reduces levels of pro-inflammatory cytokines (IL-1β, IL-2, IL-4, IL-6, TNF-α) in animal models of depression." (PMID 30200269, 2018). "We administered the Hamilton Depression Rating Scale (HAM-D) and measured systolic blood pressure (SBP), diastolic BP (DBP), mean arterial BP (MAP), pulse wave velocity (PWV), intima-media thickness (IMT), interleukin-6 (IL-6) and triglycerides." (PMID 30248896, 2018). "In conclusion, our meta-analysis found that elderly with depression had elevated peripheral levels of IL-1β, IL-6 but not CRP and TNF-α, and elderly with Alzheimer’s disease only had increased peripheral levels of blood IL-1β." (PMID 30104698, 2018). "We show that Asp358Ala is strongly associated with serum concentrations of IL-6 and CRP, but not with any of the risk factors commonly linked with inflammation, depression or psychosis." (PMID 29197507, 2018). "If the variant were associated with IL-6, CRP, depression, and psychosis, but not with the confounders, this would indicate that the variant affects psychiatric risk by altering levels of inflammation." (PMID 29197507, 2018). "Both male and female individuals with high hostility displayed higher plasma IL-6 levels than non-hostile controls only when they concurrently suffered high depression symptoms." (PMID 29623033, 2018). "Elderly with depression have higher IL-6 than controls, while those with Alzheimer’s disease did not have higher peripheral inflammatory markers." (PMID 30104698, 2018). "A significant increase in plasma IL-6, IL-1β, and TNF-α concentrations, indicating the inflammatory processes in major depressive disorder, thus supporting the cytokine hypothesis of major depression, was recorded in many studies." (PMID 30533439, 2018). "We did not have any data on depression at the time of IQ or IL-6 measurements at ages 8 and 9 years, respectively, so the possibility of reverse causality cannot be ruled out." (PMID 29140226, 2018).
depression (continued). "Further, some cytokines such as interleukin- (IL-) 1β, IL-6, and tumor necrosis factor-α (TNF-α) were believed to be contributors of the onset and progression of depression because these cytokines affected the neuron function and neuroactive molecule production which were associated with depression." (PMID 29765402, 2018). "Moreover, since depression is common in oral SCC patients, overexpression of IL-6 has been shown to lead to a poorer prognosis of the tumor." (PMID 29854027, 2018). "Furthermore, pro-inflammatory cytokines, including interleukin-6 and tumor necrosis factor alpha (TNF-α), were found to be elevated in depression." (PMID 29723340, 2018). "This positive correlation between hostility and IL-6 levels was absent among individuals with low depression symptoms." (PMID 29623033, 2018). "Inflammatory cytokines, such as interleukin (IL)-6, IL-1β, IL-8, and tumor necrosis factor (TNF)-α as well as the transcription factor NF-κB, function in the pathogenesis and development of chronic pain and depression." (PMID 30356873, 2018). "However, the present study did not replicate previous findings that have indicated increased gene expression or involvement of IL-6, IFN-γ, or TNF-α in depression." (PMID 29064428, 2017). "In a sample of older adults with depression, researchers found that the serum levels of IL-6 were higher among men, but not women." (PMID 28670290, 2017). "In this study, the ratio of IL-6 to IL-10 in the PFC of rats with depression-like phenotype was higher than rats without depression-like phenotype." (PMID 28600519, 2017). "50% of the patients treated with interferon Alfa develop depression and patients with depression had statistically higher blood levels of cytokines like tumor necrosis factor and interleukin 6 than those without depression." (PMID 27453739, 2016). "In this study, we demonstrated for the first time that depressive symptoms in COPD patients may be related to inflammatory state as confirmed with increased levels of IL-6 both in COPD and depression and also in COPD with comorbid depressive symptoms." (PMID 26403459, 2016). "IL-6 strongly activates the HPA axis and, therefore, may also contribute to the hypercortisolism observed in depression." (PMID 27918465, 2016). "They found that neither baseline IL-6 nor CRP levels behaved as predictors of the change in Beck Depression Inventory-II (BDI-II) scores during follow-up." (PMID 27918465, 2016). "Results were independent of age, adiposity, socioeconomic position, depression, smoking and alcohol consumption, physical activity, statin use, testing time, task appraisals, hormone replacement, and baseline IL-6." (PMID 26943141, 2016). "One ‘type’ of depression generating substantial interest today focuses on patients with high levels of inflammatory burden, indicated by elevated levels of C-reactive proteins (CRP) and pro-inflammatory cytokines such as interleukin 6 (IL-6)." (PMID 27765060, 2016). "It should also be noted that in depression there does not appear to be a significant correlation between IL-6 levels in blood and those in CSF." (PMID 27503474, 2016). "On the other hand, at least one study has found that somatic-vegetative symptoms of depression predicted 6-year change in IL-6 levels whereas baseline levels of neither IL-6 nor CRP were predictors of change in depressive symptoms in older individuals." (PMID 26631274, 2016). "Length of telomeres is negatively correlated with longitude of nonmedicated depression and concentration of interleukin 6 (IL-6)." (PMID 26078821, 2015). "IL-6, together with CRP, has received much attention in the pathogenesis of depression." (PMID 26617482, 2015). "Consistent with the results in the full sample, IL6 genotype was not a moderator of the relationship between chronic non-interpersonal stress and depression (b = -.39, [95% CI: -0.87 to -0.08], ΔR2 = 0.01, Δ F = 2.63, p = .11)." (PMID 25596176, 2015).
depression (continued). "Some authors suggest that the virus may be related to the pathogenesis of depression inducing pro-inflammatory cytokines production such as IL-1, TNF-alpha and IL-6." (PMID 26018525, 2015). "Increased levels of inflammatory markers such as the cytokines CRP, IL-6 and TNF-α have been measured in patients with depression, regardless of a causal link between depression and inflammation." (PMID 26231223, 2015). "A recent longitudinal study of suicide attempters with depression showed that cerebrospinal fluid (CSF) QUIN levels are increased, while CSF KA levels are decreased over a 2-year period along with an increase in IL-6 and worsening of depressive and suicidal symptoms." (PMID 26217190, 2015). "When all subjects were divided to with and without depression regardless of their cardiovascular status, there was a significant difference in serum levels of IL-8 and IL-6 between the groups (P < 0.05)." (PMID 25237578, 2014). "Similarly, most of the studies in the field are focused on definite cytokines including interleukin- (IL-)1β, IL-6, and tumor necrosis factor-α (TNF-α) since the changes in circulating IL-1β, IL-6, and TNF-α were revealed in patients with major depression." (PMID 24999483, 2014). "Finally, as expected based on a cytokine perspective of the disorder, depression during IFN-α treatment was most likely to be instigated among those individuals with the highest baseline levels of soluble IL-2 receptor (sIL-2r), IL-6, and IL-10." (PMID 23675319, 2013). "Depression also has been linked to increased levels of cytokines (specifically CRP, IL-1, and IL-6), both in patients with and without a history of cardiac disease." (PMID 23653854, 2013). "Recent evidence also suggests that enhanced inflammatory responses are additive between cigarette smoking and depression, such that depressed smokers exhibit higher levels of hsCRP, IL-6 and TNF –α than non-depressed smokers." (PMID 24228900, 2013). "Consistent with previous studies on mRNA in blood of patients with depression, both medication responders and non-responders, we found upregulation in cytokines IL-6 and IL-10 in females with medication-refractory depression." (PMID 24143878, 2013). "In a 2-year follow up prospective observational study, Pizzi investigated the relation between time domain HRV indices, IL-6, TNF-α, CRP and depression in a cohort of 415 subjects free of CADs, with at least two CAD risk factors (age, male gender, current smoking, hypertension, dislipidaemia)." (PMID 23847549, 2013). "Levels of Interleukin-6 (IL-6) and C-creative protein (CRP) indicating systemic inflammation are known to be elevated in chronic diseases including chronic obstructive pulmonary disease (COPD) and depression." (PMID 23676005, 2013). "Increased IL-1β, IL-6, and TNF-α in post-mortem PFC were also found in teenaged individuals that died by suicide, although in this study not all tissue had come from individuals that had been diagnosed with major depression." (PMID 23675319, 2013). "The main finding of this study in Caucasian patients is that the proinflammatory cytokines IL-6 and TNFα are not significantly increased and the anti-inflammatory cytokine IL-10 is not decreased in perimenopausal women with depression." (PMID 22490187, 2012). "The inflammatory theory of depression is not suitable for perimenopausal depression, since serum concentrations of the proinflammatory cytokines TNFα and IL-6 are not raised." (PMID 22490187, 2012). "Women with a lifetime history of depression have increased inflammatory biomarkers, including IL-6 and sIL-1RA, in the early puerperium as compared to women who have never suffered from depression." (PMID 22747645, 2012).
depression (continued). "Dantzer and coworkers reported that interleukin-6, a major proinflammatory cytokine, was increased in the blood of depressed patients, and a recent meta-analysis concluded that only the basal levels of IL-6 and tumour necrosis factor-alpha (TNF-α) were significantly raised in major depression." (PMID 22216404, 2011). "Cross-sectional surveys and case-control studies have also found elevated blood markers of inflammation, including CRP and IL-6, in patients with MDD relative to healthy controls, and that these markers were positively correlated with depression symptom severity." (PMID 19936106, 2009). "We did not observe differences of serum concentrations of TNF-α, sTNFRs, leptin, and IL-6 between subgroup A and subgroups B and C. It seems that circulating adipokines did not exert influence on depression levels in obese women." (PMID 19587822, 2009). "The aim of the study was to assess serum concentrations of TNF-α, TNF soluble receptors, leptin, and interleukin-6 (IL-6 ) in obese subjects with and without depression." (PMID 19587822, 2009). "Their conclusion was that depression does not necessarily influence the serum levels of IL-2 and IL-6, but it is possibly related to BMS." (PMID 16864905, 2006). "Additionally, elevated serum levels of proinflammatory cytokines (e.g., CRP, IL-6, TNF-α) in depression cross the blood-brain barrier to directly inhibit sleep-regulatory functions in the prefrontal cortex and hypothalamus, leading to sleep fragmentation and reduced slow-wave sleep 67-69." (PMID 41399386, 2026). "In vivo, a lipopolysaccharide (LPS)-induced mouse model of depression was established to assess the effects of WIS32 intervention on behavioral phenotypes, hippocampal neurochemicals (5-HT and BDNF), and serum pro-inflammatory cytokines (TNF-α, IL-1β, and IL-6)." (PMID 42238885, 2026). "Baseline hs-CRP level, but not IL-6 level, tracked depression improvement, suggesting hs-CRP may better predict immunotherapy response in depression than drug-specific biomarkers." (PMID 42160062, 2026). "Elevated levels of immune-related biomarkers, including IL-6, TNF-α, and C-reactive protein, have been consistently observed in individuals with clinical depression or suicidal behaviors, suggesting that immune dysregulation may underlie the pathophysiology of MDD and suicide risk." (PMID 41561993, 2025). "This suggests that while IL-6 may be involved in the frequency of experienced symptoms, it may not be a marker of vulnerability to full-blown clinical depression." (PMID 39902492, 2025). "Fifteen studies involving measurements of inflammatory proteins and level of depression in 1102 individuals with MS were included in the meta-analysis: five for interleukin (IL)-10 (LPS and PHA), four for tumour necrosis factor (TNF)-α, four for interferon (IFN)-γ, and four for IL-6 (LPS and PHA)." (PMID 39867847, 2025). "It is plausible that both our diabetic and non-diabetic cancer patients had high IL-6/TNF due to cancer; the people with diabetes might have had slightly higher levels, but all above a threshold that predisposes to depression." (PMID 41149069, 2025). "This study did not provide direct evidence on how IL-6 induces depression in PLWH." (PMID 40313235, 2025). "The pooled result showed that flavones increase IL-6 in blood level (pg/ml) [MD = 9.82 (95% CI: 3.56, 16.09, I2 = 8%)], sucrose preference rate [MD = 2.47 (95% CI: 0.84, 4.1, I2 = 32%)] and CORT levels [MD = −10.48 (95% CI: −19.43, −1.54, I2 = 0%)] in an animal model of depression." (PMID 39996320, 2025). "However, IL-6, IL-18, and IL-1β levels are not significantly correlated with depression in patients with CHD and STEMI." (PMID 41301929, 2025).
depression (continued). "Their review highlighted that both innate and adaptive immune dysregulation in major depressive disorder (MDD) lead to persistent elevation of CRP and IL-6, promoting microglial activation and impaired synaptic plasticity, which hypothetically could hinder the response to antidepressants." (PMID 41373439, 2025). "Exploring their potential interactions or how they differ from IL-6 in modulating a more severe state of clinical depression rather than only the frequency of depressive symptoms could provide valuable insights for future research and clinical practice." (PMID 39902492, 2025). "Additionally, CSDS significantly increases the release of IL‐6, and knockdown of IL‐6 in hippocampal microglia and IL‐6R in hippocampal astrocytes significantly enhances astrocyte survival while alleviating CSDS‐induced anxiety‐ and depression‐like behaviors." (PMID 39888279, 2025). "Older adults with depression have elevated levels of IL-6 and TNF-α compared to their non-depressed homologs, suggesting that age-related neuroinflammatory changes may play a significant role in the onset and persistence of depressive symptoms in older adults." (PMID 40305200, 2025). "Notably, IL-6 and TNF-α are potent modulators of both serotonin metabolism and hypothalamic-pituitary-adrenal (HPA) axis activity, providing a plausible link to anxiety/depression scores in our cohort." (PMID 41282285, 2025). "Moreover, elevated inflammatory cytokines like interleukin-6 (IL-6) and TNF-α in depression patients may lead to muscle atrophy and weakness." (PMID 40469587, 2025). "Laboratory data such as inflammatory markers (e.g., CRP, IL-6), which could have further explained the relationship between malnutrition and depression, were not included in the analysis." (PMID 41295296, 2025). "Notably, the group with both depressive disorder and chronic T. gondii infection exhibited a distinct cytokine profile characterized by significantly elevated TNF, IL-6, and IL-10 levels and significantly reduced IL-8 and MIF levels compared to the other groups." (PMID 40333139, 2025). "These general links between depression, inflammation, and vascular function are reflected in meta-analytic evidence for increased BBB permeability in depression, which may relate to the increased CSF levels of IL-6 in this disorder." (PMID 38483288, 2024). "Additionally, icariin downregulates the serum levels of IL-6 and TNF-α in rats with depression." (PMID 38915473, 2024). "It is proposed that inflammation is a key for depression, with approximately one-third of adults with depression exhibiting elevated levels of inflammatory cytokines, including C-reactive protein (CRP), tumor necrosis factor α (TNF-α), and interleukin-6 (IL-6)." (PMID 40226688, 2024). "Measures included the Hamilton Depression Rating Scale (HDRS-17) and the Beck Scale for Suicide Ideation/Suicide Severity Index (BSS/SSI), alongside sociodemographic data, alcohol, tobacco use, and morning blood samples, measuring plasma ACTH, cortisol, DHEA, CRP, and IL-6." (PMID 38737407, 2024). "Animal studies demonstrated that prolonged Sb exposure increased levels of inflammatory factors (interleukin-1β (IL-1β), IL-6, and TNF-α) and pro-oxidant substances (glutathione peroxidase, malondialdehyde), indicating that Sb boosts inflammatory responses, closely tied to depression." (PMID 39691784, 2024). "In the CUMS model of depression, quercetin significantly reduces the behavioral signs of stress, and raises superoxide dismutase, catalase and GSH levels while reducing lipid peroxidation and attenuating the expression and levels of the proinflammatory markers IL-6, TNF-α, IL-1β, and COX-2." (PMID 39150032, 2024). "Besides, individuals diagnosed with MDD had higher levels of nuclear factor kappa B (NF-κB) and pro-inflammatory cytokines, including interleukin-6 (IL-6) and interleukin-1β (IL-1β), when compared to the control group without depression." (PMID 38890689, 2024).